GADD45A (growth arrest and DNA damage inducible alpha)
Diseases named in the same sentence as GADD45A in open-access papers (continued):
Sharing a sentence is not in itself a finding about the gene and the disease.
cancer (continued). "The primary function of GADD45A in cancer cells is to regulate the cell cycle and inhibit cell growth." (PMID 33406670, 2021). "Mutations in well-known cancer genes located on chromosome 1p, such as NRAS (1p13.2), GADD45A (1p31.2–31.1), CDKN2C (1p32.2), RAD45(1p32) and EPB41 (1p36.2–p34), have so far only sporadically been detected." (PMID 34385566, 2021). "Meanwhile, we also chose 5 random cancer-related genes for mRNA detection, and found that GADD45A, HBP1, and SESN2 were significantly up-regulated, whereas KIF20A and TOP2A were down-regulated, compared to the 0 h group (*P < 0.05)." (PMID 32850392, 2020). "Many tumors and cancer cell lines have low levels of GADD45A and other members of the GADD45 family and, in breast cancer cases, this relationship is especially marked in TNBC." (PMID 32456160, 2020). "These functions underline an important role of GADD45A in maintaining genomic stability, DDR, and cancer transformation." (PMID 32013256, 2020). "We suggest the analysis of the DNA methylation profileof GADD45A as a potential biomarker of the cell-cycle effects ofBjussuLAAO-II in cancer cells." (PMID 31131003, 2019). "This was in agreement with previous reports that GADD45A reduces cancer progression by promoting apoptosis and cell-cycle arrest." (PMID 28445981, 2017). "It has been shown that GADD45A plays a role in inhibiting cell growth, promoting apoptosis, participating in DNA repair, and cancer cell survival." (PMID 29228625, 2017). "XPC-deficient transgenic mice are highly predisposed to several types of cancer and XPC/GADD45a knockout in mice leads to development of lung tumors." (PMID 28746345, 2017). "Consistent with findings obtained in other cancer studies, GADD45A mRNA expression was lower in ovarian patients than controls." (PMID 26422378, 2015). "For instance, growth arrest and DNA-damage-inducible, alpha (GADD45A), an essential component of many metabolic pathways that control proliferating cancer cells had relatively high expression levels in engrafted cells." (PMID 21408179, 2011). "In terms of the mechanism(s) of action of genistein, NF-kB-mediated repression of GADD45A and G expression has been shown to be essential for cancer cell survival." (PMID 18847459, 2008). "Furthermore, the knockdown of GADD45A consistently attenuated the anti-cancer phenotypes mediated by METTL1 overexpression in BC, including cell proliferation, migration, invasion, and apoptosis." (PMID 38822363, 2024). "In addition, inhibition of GADD45A and GADD45G expression is critical to the survival of cancer cells the mutation frequency and specific functions of GADD45 family members in different types of cancer remain to be determined." (PMID 38070141, 2023). "GADD45A has been recognized as a suppressor in several cancers." (PMID 35281859, 2022). "In male TA muscle, a cancer main effect was observed in Gadd45a mRNA content (p < 0.05)." (PMID 35700525, 2022). "In addition, outside those mentioned, a group of transcription factors, which dysregulation has been widely associated with cancer phenotype was identified, including DEGs such as BCL6, DDIT3, GADD45A, HMGA2, and ID2." (PMID 35359411, 2022). "Recent reports have suggested that decreased GADD45A expression due to abnormal methylation may contribute to cancer cell resistance to radiotherapy through the PI3K/AKT signaling pathway." (PMID 36233241, 2022).
cancer (continued). "Besides the promoter methylation, the activated NF-κB also was suggested to result in the repression of Gadd45 a and Gadd45 g in cancers." (PMID 29225771, 2017). "This may be due to the inherent function of Gadd45a as a stress response protein, wherein the presence of an oncogene results in its induction during the early stages of cancer development." (PMID 28086219, 2017). "In contrast, GADD45A reduces cancer progression by promoting apoptosis and cell-cycle arrest." (PMID 28445981, 2017). "In addition, down-regulation of GADD45A promoted by the NF-κB transcription factor is essential for cancer cell survival." (PMID 28035074, 2017). "Furthermore, cancer cells with GADD45A knockdown can evade the apoptotic pathway, and GADD45A elicits its function through activation of JNK and p38 kinases." (PMID 26871431, 2016). "GADD45A is a target for therapeutic interventions in cancer." (PMID 25182732, 2014). "However, in Her2+/Neu and Triple Negative breast cancers, the levels of Gadd45a were low, similar to the levels observed in normal breast tissue." (PMID 23706118, 2013). "In addition, Egfr (epidermal growth factor receptor), Gadd45A (growth arrest and DNA-damage-inducible protein) and Id1 (inhibitor of differentiation) are well known to function in cancer pathways." (PMID 23922661, 2013). "Downregulation of EPB41L3, but not of GADD45A, was associated with promoter hypermethylation, which was detected in 79% of carcinoma samples." (PMID 17280610, 2007). "However, it has already been shown that DDIT3 and GADD45A are repressed by NFκB in cancer cells to ensure cell survival and may therefore be important for adaptation." (PMID 39337613, 2024). "Thus, GADD45A is involved in the pathogenesis of many types of human cancers." (PMID 28821714, 2017). "The induction and activation of mda-7/IL-24 by NSAIDs result in the upregulation of GADD45A and GADD45G, which are crucial for the execution of cancer cell death through JNK activation." (PMID 41018072, 2025). "Growth arrest and DNA damage-inducible 45 alpha and beta (GADD45A, GADD45B) genes, which are involved in the MAPK pathway and overexpressed in our study, have important roles especially in cancer mechanism." (PMID 39838121, 2025). "In female mice both plantaris and TA muscle, a cancer main effect was noted in Gadd45a mRNA content, where LLC group displayed an ~1- and 2-fold greater mRNA levels of Gadd45a when compared with PBS, respectively (p < 0.05)." (PMID 35700525, 2022). "In males plantaris muscle a cancer main effect was noted, where LLC group displaying ~1-fold more mRNA content of Gadd45a when compared with PBS (p < 0.05)." (PMID 35700525, 2022). "The genes involving cell cycle control, DNA replication, apoptosis, senescence and autophagy in cancer pathways including CDK4, E2F1, Bax, CDKN1A, GADD45A, FAS, GABARAPL2, and SQSTM were significantly upregulated." (PMID 34305605, 2021). "Taken together, our findings provide strong evidence that NPM, E3 ligase RNF2, and GADD45a directly and functionally control powerful RAS effector networks that are vital in multiple cancer processes." (PMID 34224728, 2021). "Due to high homology of GADD45 genes, GADD45A and GADD45G exert similar effects on the development of cancers." (PMID 34601500, 2021). "GADD45A prevents the EMT by controlling the expression of matrix metalloproteinases (MMPs) and β-catenin distribution within cancer cells." (PMID 28445981, 2017).
cancer (continued). "Jun, CSF2 and IL-8 showed increased expression in IMR90 cells, whereas, NFκB1, NFκBIA, FN1 (fibronectin 1), GADD45A, BIRC2, TMEPAI (prostate androgen induced RNA) and CEBPB (CCAAT/enhancer binding protein) were up regulated in cancer cells." (PMID 22321936, 2012). "Several genes conspicuous in the present study are subject to DNA hypermethylation in other cancers, prominently EPB41L3 and GADD45A." (PMID 17280610, 2007). "On the other hand, in transcriptional misregulation in the cancer signaling pathway, only MYCN expression was notably decreased, and the expression of 20 genes, including GADD45A, CXCL8, JMJD1C, RUNX1, and H3C14, was significantly increased in NHEKs upon HPV8 E7 expression." (PMID 35665406, 2022). "Another important message coming from that research was that a reduced activity of GADD45A may result in increased methylation of the tumor suppressor MLH1, which can contribute to genomic instability that is typical for cancer." (PMID 32013256, 2020). "Overall, high expression of GADD45A was found in 72.3% (303/419) cancer tissues and 37.9% (44/116) adjacent noncancerous tissues." (PMID 30128181, 2018). "Therefore, similar to other renowned cancer related proteins (e.g. E2Fs, p21, GADD45A, MYC and RUNX1), Trib2 obeys the Goldilocks principle in cancer biology; too little or too much are both pro-tumorigenic." (PMID 29670085, 2018). "It has been shown that blocking GADD45a expression by constitutive antisense expression sensitized cells to be killed by UV or by cis-platinum (II) diamine-dichloride (CDDP, or cisplatin), a cancer chemotherapy drug which produces DNA cross-links." (PMID 28098804, 2017). "A search for Gadd45a on public cancer microarray databases fails to provide statistically significant data to support our findings in this report that Gadd45a expression is elevated based on hormone receptor status." (PMID 23706118, 2013). "In addition, GADD45A and GADD45G are repressed by the activated members of the NFκB family in various types of cancer." (PMID 24351910, 2013). "Indeed, genistein treatment of NCCIT cells led to the induction of GADD45A and GADD45G expression with other cancer types." (PMID 18847459, 2008). "Finally, through gene expression analysis, we identified signaling molecules that might contribute toward TRAIL and MSC-TRAIL resistance in CD133+ CSCs, and uncovered NFKB1, BAG3, MCL1, GADD45A, and HRK as potential anti-cancer genes that could increase sensitivity of NSCLC to MSC-TRAIL therapy." (PMID 31466290, 2019). "After TNFα, TRAF3 or GADD45A is knockdown in the HCC cells, both mono-treatments and combination treatment failed to induce apoptosis; and the combination treatment failed to exhibit its synergistic effect in inhibiting the cancer growth." (PMID 34025421, 2021). "In our study, we could not separately evaluate the contribution TNFα, TRAF3 and GADD45A in the combination treatment-enhanced apoptosis because knockdown of either TNFα, TRAF3 or GADD45A can completely abolish the treatment-induced apoptosis and the synergy in inhibiting cancer cell growth." (PMID 34025421, 2021).
infection (15 papers, 2010 to 2025). The state of being infected such as from the introduction of a foreign agent such as serum, vaccine, antigenic substance or organism. "CD79A was significantly downregulated in severe cases, correlating with impaired B-cell responses and cytotoxic immunity, while GADD45A, upregulated in severe infections, linked to oxidative stress and neutrophil-driven inflammation." (PMID 40677720, 2025). "After transfection with either GADD45A‐RNAi or Control‐RNAi and subsequent PPRV infection, we found that GADD45A knockdown led to reduced levels of PPRV N protein (p < 0.05), lower genome copy numbers (p < 0.01), and decreased viral titers (p < 0.01)." (PMID 40548900, 2025). "Three out of fourteen genes (ATF4, CHOP, and GADD45A) involved in the activation of the PERK pathway during ER stress were upregulated after P150 infection compared to P1." (PMID 35992665, 2022). "Infection with the shRNA1 lentivirus led to a 70% reduction in the level of Gadd45a, compared to cells treated with control shRNA." (PMID 32719383, 2020). "The reduction of SOD-1, SOD-2, catalase and GADD45A was much more pronounced in the livers of FoxO3a−/− mice following infection with ST." (PMID 27599659, 2016). "Previous studies have identified immune-related genes, such as IFNs and chemokines, as potential biomarkers for RSV severity.However, the novelty of CD79A and GADD45A lies in their specific association with hospitalization needs rather than general infection status." (PMID 40677720, 2025). "Upon infection of well‐maintained and contamination‐free GAM cells with the PPRV (Nigeria 75/1 strain), we observed a time‐ and dose‐dependent upregulation of GADD45A mRNA expression (p < 0.01)." (PMID 40548900, 2025). "Infection with ST resulted in substantial reduction in the expression of SOD-1, SOD-2, catalase and GADD45A, perhaps to allow ROS levels to build-up to control the pathogen." (PMID 27599659, 2016). "To further investigate the interaction between GADD45A and PPRV proteins, we transfected HEK293T cells with HA‐GADD45A either alone or in combination with various PPRV proteins (Flag‐P, Flag‐C, Flag‐M, Flag‐V, Flag‐N, Flag‐H, Flag‐F) along with the IFN‐β‐Luc plasmid, followed by infection with SeV." (PMID 40548900, 2025).
adenocarcinoma (2 papers, 2018 to 2021). A common cancer characterized by the presence of malignant glandular cells.
bacterial infections (1 paper, 2025). "Among the genes, BMX and GRB10 are particularly associated with immune-regulating signaling pathways, while GADD45A is mainly involved in the defense response to bacterial infections." (PMID 40230692, 2025).
brain diseases (1 paper, 2024). "Therefore, both PTPRO and GADD45A may play significant roles in the pathogenesis of brain diseases." (PMID 38212777, 2024).
endocrine disorder (1 paper, 2025). "The loss of Gadd45a in mice caused aberrant follicle development and endocrine disorder." (PMID 40916072, 2025).
heart disease (1 paper, 2025). "Overall data identify GADD45A as an essential factor during heart disease." (PMID 40301189, 2025).
intestinal diseases (1 paper, 2025). "Several studies have indicated that GADD45A may serve as a key target for treating intestinal diseases." (PMID 40236773, 2025).
GADD45A also shares sentences with these, for which no sentence is quoted: schizophrenia (4 papers); osteoarthritis (3); pancreatic ductal adenocarcinoma (3); vitiligo (3); chronic obstructive pulmonary disease (2); Coma (2); diabetes (2); head and neck cancer (2); Hypertension (2); intrahepatic cholangiocarcinoma (2); kidney diseases (2); lung squamous cell carcinoma (2); metabolic disease (2); neurodegenerative disease (2); psychiatric diseases (2); xeroderma pigmentosum (2); adenoma (1); Airway obstruction (1); Allergy (1); anemia (1); Arthritis (1); Ataxia (1); autism (1); autism spectrum disorder (1); basal cell carcinoma (1); central nervous system diseases (1); Cerebral ischemia (1); cholangiocarcinoma (1); Cirrhosis (1); coagulopathy (1).
A further 57 diseases each share a sentence with GADD45A in 1 paper.